OPA1 (OPA1 mitochondrial dynamin like GTPase)
Diseases named in the same sentence as OPA1 in open-access papers (continued):
Sharing a sentence is not in itself a finding about the gene and the disease.
heart failure (continued). "Using a post-MI rat heart failure model and human dilated and ischaemic cardiomyopathy tissue samples, the fragmentation of the mitochondria due to decreased myocardial levels of OPA1 was demonstrated." (PMID 25987420, 2015). "Previously we reported that the fusion protein optic atrophy 1 (OPA1) is decreased in heart failure." (PMID 23316298, 2012). "Additionally, the reduced expression of the transcriptional target Opa1 in the hearts of the aged sedentary group suggests impaired mitochondrial fusion, leading to abnormal mitochondrial dynamics and contributing to heart failure." (PMID 39571159, 2024). "Given that OPA1 is a crucial protein involved in maintaining mitochondrial dynamics, it has been demonstrated that an excessive proteolysis of OPA1 can trigger mitochondrial fragmentation, consequently leading to heart failure in mice." (PMID 38267829, 2024). "Altered OPA1 function was proposed to lead to the pathogenesis of heart failure." (PMID 36776252, 2023). "Opa1 protein was significantly decreased after heart failure and myocardial infarction." (PMID 33637715, 2021). "QSG could also act on the expression of mitochondrial fusion/split protein, upregulate the expression of MFN1/2 and OPA1, inhibit the expression of DRP1 and FIS1, and reduce mitochondrial disorders and oxidative stress damage caused by heart failure." (PMID 35003305, 2021). "The reason for the decline of OPA1 levels in heart failure requires further investigation." (PMID 25987420, 2015). "A higher s-OPA1/l-OPA1 ratio promotes mitochondrial fragmentation and may promote a metabolic shift in the myocardium from its normal substrate (fatty acids) toward glucose, impaired mitochondrial energetics, energy depletion, and heart failure." (PMID 32973679, 2020). "However, mfn1/2 and OPA1 overexpression may improve mitochondrial functions and inhibit cardiac failure." (PMID 24675698, 2014). "Numerous studies have demonstrated that OPA1 and MFN2 expression are reduced and that Drp1 levels are increased in patients with heart failure." (PMID 40507126, 2025). "Another study demonstrated that Mfn2 and OPA1 levels are reduced, while DRP1 and FIS1 levels are elevated in heart failure in dogs and humans." (PMID 37371979, 2023). "In various disease models, such as heart failure, kidney ischemia, or neurodegenerative diseases, OMA1-mediated cleavage of OPA1 at the S1 site does not cause mitochondrial fusion." (PMID 35395832, 2022). "Although no cardiac phenotype has been directly associated with OPA-1 mutations in humans, OPA-1 levels are reduced in heart failure, and electron micrographs of explanted hearts from transplant recipients reveal small and fragmented mitochondria, consistent with decreased fusion." (PMID 40450326, 2025). "In turn, mild overexpression of OPA1 protects against cardiac and cerebral ischemia, while the metalloendopeptidase OMA1 (which is activated in response to stress and mediates OPA1 proteolytic processing) plays a central role in mediating ischemia-induced heart failure and cardiac hypertrophy." (PMID 34832998, 2021).
Obesity (29 papers, 2013 to 2026). Accumulation of substantial excess body fat. "AMPK is involved in the molecular mechanisms of aging, obesity, and protection against drug-induced liver injury by regulating the mitochondrial fusion-related protein OPA1 and mitochondrial activity and dynamics." (PMID 40646155, 2025). "Conversely, OPA1 overexpression protects against diet-induced obesity by preventing BAT whitening and stimulating WAT browning, potentially through fumarate-driven activation of KDM3A51." (PMID 40750944, 2025). "Another transcript revealed by the direct comparison of the obesity-resistant NR to obesity-prone SR phenotypes was optic atrophy 1 (Opa1), a protein essential for mitochondrial fusion, lipid, metabolism, and for supporting cellular energetics." (PMID 38276304, 2024). "Opa1tg mice with ubiquitous mild Opa1 overexpression were slightly resistant to high-fat diet-induced obesity, glucose intolerance, and hepatic steatosis compared to their littermate controls." (PMID 37680891, 2023). "FGF21 increases metabolic rates under baseline conditions but is dispensable for the resistance to diet-induced obesity (DIO) reported in OPA1 BKO mice." (PMID 37819027, 2023). "By contrast, reduced OPA1 expression in overnutrition impairs adipocyte plasticity, thus exacerbating the obesity phenotype." (PMID 36457729, 2022). "OPA1 promotes autonomous browning of adipocytes, and brown adipose tissue reduces obesity through energy conversion." (PMID 36457729, 2022). "Optic atrophy 1 (OPA1) deletion in brown adipose tissue (BAT) prevents diet-induced obesity and insulin resistance." (PMID 33944779, 2021). "These confirm the close relationship between Opa1 and mitochondrial insulin-stimulated energy metabolism, which provides a basis for its regulatory role in obesity and diabetes." (PMID 31551926, 2019). "In addition to DILI, we also tested the effect of OPA1 LKO on metabolic burden by diet-induced obesity model." (PMID 37872238, 2023). "Moreover, in humans with insulin resistance and obesity, the levels of OPA1 in the skeletal muscle are reduced compared to healthy patients." (PMID 35846351, 2022). "In particular, several authors have argued that obesity is characterised by a reduced gene expression of OPA1 and MFN1 in rat liver and skeletal muscle, which may contribute to mitochondrial dysfunction." (PMID 35883794, 2022). "However, mechanisms independent of FGF21, but dependent on ATF4 induction, promote resistance to diet-induced obesity in OPA1 BAT KO mice." (PMID 33944779, 2021). "The expanding evidence also displays the involvement of Opa1 in obesity and diabetes." (PMID 31551926, 2019). "Therefore, it is urgent to elucidate how Opa1 processing regulates mitochondrial metabolism in obesity and diabetes." (PMID 31551926, 2019). "Similarly, resistance to obesity was observed in a mouse model of Opa1 haploinsufficiency." (PMID 37680891, 2023). "This study also showed that, in the HFD-Con group, where obesity was induced, the expression of proteins related to mitochondrial fission, Drp1 and Fis1, increased, whereas the expression of proteins related to mitochondrial fusion, Mfn1, Mfn2, and Opa1, decreased." (PMID 31010272, 2019). "We recently showed that selective deletion of the mitochondrial fusion protein optic atrophy 1 (OPA1) in brown adipocytes (OPA1 BKO) leads to GDF15 secretion, partially mediating resistance to diet-induced obesity (DIO), and improving thermoregulation." (PMID 41974995, 2026). "OPA1 BKO mice have higher resting metabolic rates and are completely resistant to diet-induced obesity (DIO)." (PMID 37819027, 2023). "Conversely, as in OPA1 BKO mice, long-term induction of GDF15 attenuated progression of obesity by increasing energy expenditure in DIO, while FGF21 was dispensable for this phenotype." (PMID 37819027, 2023).
Obesity (continued). "As part of the mitochondrial fusion machinery, mitofusin 1 and 2 (MFN1 and MFN2, respectively) were significantly increased by DPR, irrespective of obesity, whereas optic atrophy 1 (OPA1) expression was unchanged." (PMID 41549510, 2026). "This fragmentation is exacerbated by impaired mitochondrial fusion proteins: OPA1 and MFN2 expression is reduced in skeletal muscle from individuals with obesity and T2DM, and OPA1 itself can be oxidatively modified, with S-nitrosylated OPA1 detected in stressed tissues." (PMID 41226411, 2025). "OPA1 BKO mice developed metabolic adaptations that increased their resting metabolic rates and improved insulin sensitivity under baseline conditions and promoted resistance to diet‐induced obesity (DIO)." (PMID 40897647, 2025). "Brown adipose tissue (BAT)-derived fibroblast growth factor 21 (FGF21) does not mediate resistance to diet-induced obesity in optic atrophy 1 (OPA1) BAT knockout (KO) mice." (PMID 33944779, 2021). "A series findings by Zorzano's group also showed that altered expression of OPA1 and decreased expression of MFN2 participated in the development of obesity and type 2 diabetes in both patients and rodent models, which highlighted the importance of MFN2 in metabolism." (PMID 24658162, 2014). "In this context it is noteworthy that 20-month old Opa1 mutant mice showed no signs of obesity under regular animal housing conditions, while all animals in the control group were morbidly obese at this age." (PMID 24067127, 2013). "However, induction of FGF21 levels in adult obese mice, by inducible deletion of the mitochondrial fusion protein optic atrophy 1 (OPA1) in skeletal muscle, was able to reverse DIO, suggesting that induction of this pathway after the onset of obesity may still exert beneficial metabolic effects." (PMID 37818094, 2023). "While another study found Mfn1 and Mfn2 but not Opa1 were decreased, and Drp1 and Fis1 were increased in skeletal muscle of HFD-induced obesity mice." (PMID 29245950, 2017).
Parkinsonism (27 papers, 2009 to 2026). Characteristic neurologic anomaly resulting from degeneration of dopamine-generating cells in the substantia nigra, a region of the midbrain, characterized clinically by shaking, rigidity, slowness of movement and difficulty with walking and gait. "Some affected family members had other neurological comorbidities concomitantly, such as spastic paraparesis and parkinsonism, as described in other OPA1-associated ADOA families." (PMID 34853716, 2021). "Neural progenitor cells (NPCs) from two OPA1 missense mutations causing Parkinsonism and dementia presented bioenergetic defect, mitochondrial network fragmentation, increased ROS levels, and alteration in the lysosome pathway." (PMID 34177786, 2021). "In severe cases, neurodegeneration due to OPA1 mutations has been reported to contribute to Parkinson’s disease." (PMID 34299348, 2021). "Genetic evidence suggests that the pathways of mitochondrial quality control (PARKIN, PINK1, DJ-1, FBOX7) and mitochondrial fusion/fission dynamics (OPA1) are implicated in PD and parkinsonism." (PMID 33381501, 2020). "OPA1 has been implicated in various other diseases as well, including normal tension glaucoma, multiple sclerosis-like illness, Parkinson’s disease and dementia, and cardiomyopathy." (PMID 39177028, 2024). "Recently, the association between OPA1 and parkinsonism was also noticed." (PMID 36611869, 2022). "The main pathological features, such as mitochondrial network fragmentation and reduced energetic capacity, have been also reproduced in induced pluripotent stem cell (iPSC)-derived dopaminergic neurons from patients carrying OPA1 mutations associated with Parkinsonism and DOA." (PMID 33806088, 2021). "Disturbed mtDNA maintenance with loss of mtDNA integrity is a pathological hallmark shared by a number of neurodegenerative phenotypes, including monogenic diseases caused by OPA1 mutations and more complex, late-onset neurological diseases, such as Parkinson’s disease." (PMID 34589289, 2021). "However, cognitive deficits have been reported for OPA1 mutations leading to Behr syndrome and Parkinson-like symptoms." (PMID 33094281, 2020). "Recently, missense mutations in OPA1 causing decreased protein expression were associated with parkinsonism and cognitive decline, suggesting that under certain conditions, loss of OPA1 function may compromise dopaminergic cell viability." (PMID 29604226, 2018). "Both the cell lines showed a reduction in oxygen consumption rate (OCR), complex I levels, and activity, whereas only neurons derived from the patient with Parkinsonism presented mitochondrial fragmentation and an increase of the OPA1 short forms." (PMID 34177786, 2021). "Here, we used a tractable induced pluripotent stem cell (iPSC)‐based model to capture the biology of OPA1 haploinsufficiency in cases presenting with classic eye disease versus syndromic parkinsonism." (PMID 29604226, 2018). "For Parkinson’s disease, it was shown that these proteins Mfn2, Opa1, Drp1, and Fis1, which are involved in the control of mitochondrial fusion and fission and are downregulated in a rotenone-induced Parkinson’s disease model remained at a normal level by resveratrol administration." (PMID 37232719, 2023). "Dopaminergic neurons carrying an OPA1 mutation causing haploinsufficiency were generated via iPSCs from two patients belonging to the same family that, interestingly, developed different clinical phenotypes: isolated DOA or DOA with syndromic Parkinsonism." (PMID 34177786, 2021). "We show that Optic Atrophy 1 (OPA1) and sorting nexin 9 (Snx9)-dependent MDVs are required to target mitochondrial proteins to EVs, while the Parkinson’s disease-related protein Parkin blocks this process by directing damaged mitochondrial content to lysosomes." (PMID 33785738, 2021).
Parkinsonism (continued). "A microfluidic nigrostriatal pathway (a brain structure composed primarily of dopaminergic neurons) on-a-chip technique, consisting of iPSC-DANs and striatal medium spiny neurons, was developed to study functional synapse connections in the OPA1 Parkinson’s disease model." (PMID 34299348, 2021). "In addition, downregulated OPA1 has been reported in other neurodegenerative diseases models, such as Alzheimer’s disease, Parkinson’s disease, Huntington’s disease (HD), and retinal ischemia–reperfusion-related diseases." (PMID 31551424, 2019). "The absence of a secondary pathogenic mutation on exome sequencing of patient DNA to explain this phenotypic difference between Opa1P and Opa1 lines suggests that syndromic OPA1 parkinsonism may arise from a modifier effect of the primary mitochondrial defect." (PMID 29604226, 2018). "Nevertheless, understanding how L‐OPA1 processing varies in syndromic OPA1 and common diseases of dopaminergic cell loss such as Parkinson's and promoting L‐OPA1 stability (eg, by OMA1 inhibition) could pave the way for novel targeted therapies against mitochondrial dysfunction in neurodegeneration." (PMID 29604226, 2018).
glaucoma (26 papers, 2009 to 2025). Increased pressure in the eyeball due to obstruction of the outflow of aqueous humor. "Experimental glaucoma models demonstrate that OPA1 overexpression protects against RGC loss by enhancing mitochondrial fusion and parkin-mediated mitophagy." (PMID 39201313, 2024). "OPA1 was an obvious candidate disease-susceptibility gene in glaucoma and we recently carried out a systematic screen of the entire coding region using a well-characterised POAG cohort from the North of England." (PMID 21112411, 2011). "The association between OPA1 and mitochondrial zinc metallopeptidases can be another potential research focus with respect to providing insight into the roles of zinc and the mitochondria of RGCs in glaucoma." (PMID 34447755, 2021). "And yet, also OPA1 polymorphisms are discussed to be associated with certain forms of glaucoma." (PMID 24067127, 2013). "Results of meta-analysis for OPA1 polymorphisms and risk of primary open angle glaucoma." (PMID 22879959, 2012). "We hypothesized that elevated pressure, a major risk factor for glaucoma, may directly trigger mitochondrial structural changes associated with release of OPA1 and cytochrome C into the cytoplasm and induce apoptotic cell death in RGCs." (PMID 19169378, 2009). "Thus, the present observations that pressure-induced mitochondrial fission and OPA1 release occur before the onset of apoptosis raise the possibility that preventing release may protect against RGC damage or loss in glaucoma." (PMID 19169378, 2009). "Variants and reduced expression of OPA1, involved in mitochondrial fission and known for its mutation in DOA, have been linked to glaucoma." (PMID 39201313, 2024). "There is compelling evidence implicating mitochondrial dysfunction, specifically complex I dysfunction and OPA1 gene involvement, in glaucoma pathogenesis." (PMID 39201313, 2024). "OPA1, a mitochondrial fusion-related protein, is responsible for ADOA, and patients with glaucoma reportedly carry variants of this gene." (PMID 36901786, 2023). "In fact, the suppression of Drp1, a protein involved in mitochondrial fission, or the overexpression of OPA1, a protein involved in mitochondrial fusion, protects RGCs and prevents their axonal degeneration in a mouse glaucoma model." (PMID 36901786, 2023). "Previously, it has been shown that increased expression of OPA1 promoted RGC survival in a mouse model of glaucoma, and prevented mitochondrial fission and promoted RGC-5 survival following elevated hydrostatic pressure as well." (PMID 30323741, 2018). "Further studies will be needed to clarify the molecular mechanism among OPA1, Bax, and Bcl-2 in experimental glaucoma." (PMID 30323741, 2018). "In this study, we explored the mechanism involved in OPA1 mediated neuroprotection and its relationship with parkin dependent mitophagy in experimental glaucoma models." (PMID 30323741, 2018). "Increased OPA1 expression attenuated Bax expression, improved mitochondrial health and mitochondrial surface area in experimental glaucoma." (PMID 30323741, 2018). "In summary, our findings demonstrate that overexpression of OPA1 protects RGCs by ways of enhancing mitochondria fusion and parkin mediated mitophagy in experimental glaucoma." (PMID 30323741, 2018). "Taken together, our data are consistent with the notion that OPA1 exerted a significant protective effect on RGCs via promoting mitochondrial fusion in experimental glaucoma." (PMID 30323741, 2018). "Three other studies have found a similar association between these two OPA1 SNPs and NTG, supporting a possible role of the OPA1 protein in modulating disease susceptibility to glaucoma." (PMID 21112411, 2011). "Finally, OPA1 and MFN2, which regulate mitochondrial fusion and axonal transport, are implicated in glaucoma through disruption of mitochondrial dynamics, compromising the long-range energy supply critical for RGC function." (PMID 40964175, 2025).